TLR5 (toll like receptor 5)
Diseases named in the same sentence as TLR5 in open-access papers (continued):
Sharing a sentence is not in itself a finding about the gene and the disease.
tumor (continued). "On the other hand, we found that rFlic mixed with rE7m could induce similar levels of anti-tumor activity to rFlicE7m because rFlic preserves both TLR5 and inflammasome activity (data not show)." (PMID 27063435, 2016). "Ablation of tumour necrosis factor receptor (TNFR)-1/-2, Myeloid Differentiation primary response gene 88 or Toll-like receptor (TLR)-5, the bacterial flagellin receptor, but not other innate immune sensors, in radiosensitive leukocytes protects against tumour formation." (PMID 25575023, 2015). "Flagellin did not induce tumours when injected into TLR-5−/− BM chimeras." (PMID 25575023, 2015). "More importantly, we found that compared with phosphor‐autoradiography imaging, we could more clearly visualize tumour location and edge with green fluorescence labelled tumour cells, while TLR5+ tumour without virus transfected only showed radioactivities accumulation." (PMID 31576678, 2019). "The promotion of tumor formation in 85As2 cells may be independent of TLR5 signaling." (PMID 30410674, 2018). "Flagellin, a TLR5 agonist, combined with IFN-γ did not induce any tumor cell growth inhibition by BMDMs, but it activated the macrophage cell line J774.A1." (PMID 29123526, 2017). "At present, little is known about the role of TLR2 and TLR5 in MCL, although their expression has been frequently reported to exhibit tumor-promoting signaling rather than antitumor responses." (PMID 27123851, 2016). "In this study, we utilize TLR5-negative tumors ruling out direct killing or alteration in proliferation of the tumors by CBLB502, leaving the host as the sole mediator of tumor clearance." (PMID 24454895, 2014).
cancer (56 papers, 2008 to 2025). A tumor composed of atypical neoplastic, often pleomorphic cells that invade other tissues. "Although associated with various malignant tumors, the role of toll-like receptor 5 (TLR5) in TNBC remains uncertain." (PMID 31852883, 2019). "This is the first study to report that LIF production is promoted by TLR5 in cancer cells as a mechanism underlying the worsening of cancer cachexia." (PMID 30410674, 2018). "Among the diverse array of TLR ligands evaluated as adjuvants for cancer vaccines, flagellin, the cognate ligand for TLR5, has shown significant efficacy when co-formulated with peptide or protein antigens." (PMID 40118497, 2025). "TLR5 has emerged as a promising target in cancer immunotherapy, owing to its ability to activate both innate and adaptive immune responses." (PMID 40444793, 2025). "We were among the first groups to discover that TLR5 functions not only in innate immune cells but also in cancer epithelial cells." (PMID 38903515, 2024). "In squamous cell carcinoma, M1-derived exosomes containing HOTTIP inhibit cancer cell proliferation and induce apoptosis by activating the TLR5/NF-κB pathway." (PMID 38473915, 2024). "Studies have also demonstrated that activation of TLR-5 promotes apoptosis in cancer cells through the activation of caspases and the upregulation of pro-apoptotic factors." (PMID 38090147, 2023). "TLR1, TLR2, TLR3, TLR4, and TLR5 expression levels were high across the six immune subtypes in the pan-cancer data; TLR6, TLR7, TLR8, and TLR10 expression levels were moderate; and TLR9, TLR12P, and TLR8-AS1 expression levels were extremely low." (PMID 35801728, 2022). "Upon stimulation with flagellin, from mobile bacteria, TLR5 activates a signaling pathway that regulates several processes including insulin resistance, maintenance of lung and intestinal homeostasis and cancer." (PMID 34884547, 2021). "The Toll-like receptor 5 (TLR5) agonist entolimod, a derivative of Salmonella flagellin, has therapeutic potential for several indications including radioprotection and cancer immunotherapy." (PMID 33846531, 2021). "A study suggested that Salmonella flagellin, a TLR5 agonist, improves the therapeutic index of cancer radiotherapy." (PMID 32365611, 2020). "Bacterial flagellin, a TLR5 agonist, has been demonstrated strong anti-cancer effect in lots of animal models." (PMID 33469538, 2020). "TLR5 is expressed in lung and intestinal epithelial cells, human endometrium, bladder, granulosa cells leukocytes, adipocytes, and some cancer cells, among others." (PMID 32854231, 2020). "Currently, the particular function and exact mechanism of TLR5 signaling pathways in cancer cells remains poorly understood, and the abnormal expression of TLR5 has been noted as a potential biomarker for tumors." (PMID 24932259, 2014). "Although increasing evidence has shown that TLR5 plays a prominent role in cancer progression, its expression and role in HCC remain unclassified." (PMID 24932259, 2014). "Current studies show that TLR5 is expressed in multiple epithelial tissues, but also by several cancer cells." (PMID 24932259, 2014). "Previously, much attention has been paid to investigating the role of TLR5 in cancer progression and metastasis." (PMID 24932259, 2014). "Toll-like receptor 5 (TLR5) is overexpressed in several cancers and metastases, and presents an enticing target for molecular imaging of primary tumors." (PMID 24932259, 2014). "Triggering of TLR5 in cancer cells inhibits cancer cell proliferation and elicits strong antitumor activity." (PMID 24466264, 2014). "The genetic variability of TLR5 in humans affects cancer progression and immune surveillance." (PMID 40444793, 2025). "Microbiota-TLR5 interactions in mice modulate systemic inflammation and cancer, which may be important for patients with breast and OV." (PMID 39475915, 2024). "Flagellin, a TLR5 agonist, is widely used in anti-cancer treatment." (PMID 37822929, 2023).
cancer (continued). "Similarly, recombinant flagellin, which stimulates TLR5, is also being clinically evaluated as an adjuvant therapy in various indications, including cancer." (PMID 36140335, 2022). "There is little information in functionality of TLR5 in cancer." (PMID 36539522, 2022). "While some TLRs may be procarcinogenic, such as TLR2-MyD88, others may play a protective role, inhibiting growth of cancer cells and having potent antitumoural activity, such as TLR5." (PMID 33716996, 2021). "In summary, NME3 may strengthen cancer immunotherapy as an unrecognized pro-inflammatory cytokine in TLR5 downstream signaling." (PMID 33469538, 2020). "The anti-cancer effects of TLR5 agonists stem from the dependence on TLR5 to activate NF-κB." (PMID 33469538, 2020). "Due to the flagellin-induced IL6, which is known to inhibit apoptosis in many cancer cell types, we measured the effects of flagellin on the caspase-1 activity of the C26 cells together with either TLR5 antagonist or genipin, which inhibits NLRP3-mediated inflammasome activation." (PMID 31731747, 2019). "Due to the high importance of TLR5 in induction of both innate and adaptive immunity flagellin is now used as an adjuvant of different vaccine preparations and an anti-cancer agent in several clinical trials, as well as a potential agent to reduce radiation toxicity." (PMID 31083432, 2019). "Considering of TLR5 expression co‐related with cancer progression, we postulated that TLR5 may be as a predictor of TNBC development, so we choose TNBC cell line to investigate whether it could be a target molecule of non‐invasively diagnosis for TNBC." (PMID 31576678, 2019). "Further studies of whether TLR5 or IRAK-1/4 antagonists improve cancer cachexia symptoms are necessary." (PMID 30410674, 2018). "Recent findings suggest the TLR5 expression level affects cancer progression and development." (PMID 29179462, 2017). "In particular, bacterial flagellin was used as a TLR5 agonist in cancer therapy." (PMID 27687589, 2016). "In this study, we investigated whether TgPLP, a TLR11 agonist in mice and a TLR5 agonist in humans, represents a vaccine adjuvant for cancer therapy." (PMID 27687589, 2016). "Thus, MAP1S controls the TLR5 signaling pathway in cancer cells." (PMID 24466264, 2014). "The flagellin protein from S. typhimurium is a potent activator of the innate immune response through binding of toll-like receptor 5 (TLR5), and many cancer cells will express TLR5 even though the normal tissue does not." (PMID 37628585, 2023). "Ligands of TLR2 and TLR5 also induced migration of NCI-H292 cells, suggesting that both cancer growth and spreading can be affected by certain TLR signals." (PMID 18167552, 2008). "A pan-cancer analysis identified TLR4 and TLR5 as prognostic genes in ACC." (PMID 36899891, 2023). "TLR5, TLR7, and TLR8-AS1 were found to be significant in seven cancers each." (PMID 35801728, 2022). "Here, the novel vaccine against cancer, Mobilan, appears to be especially promising due to its creative design, which allows it to be effective regardless of TLR5 expression on the targeted cancer cells." (PMID 33499143, 2021). "TLR5 is expressed highly in some cancer cells, but is not expressed on mouse macrophages and conventional dendritic cells." (PMID 24466264, 2014). "However, the biological importance of TLR5 to tumorigenesis and cancer development is still not completely understood." (PMID 29179462, 2017). "The reason for these different outcomes of TLR5 signaling in different cancers is not clear." (PMID 24466264, 2014).
bacterial infection (40 papers, 2012 to 2026). "Although not differentially expressed among fry samples from three rainbow trout lines with different susceptibilities to F. psychrophilum, a gene annotated as tlr5 was induced to higher levels after bacterial infection in the susceptible family than in the other families." (PMID 39712009, 2024). "Notably, TLR5 specifically recognizes flagellin from bacteria, and bacterial infection has been associated with the increased occurrence of neurodegenerative diseases, such as AD." (PMID 32912327, 2020). "The TLR5 activation via flagellin may prevent bacteria to evade the host's innate immune responses and alter the level of tissue damage associated with late-stage bacterial infection." (PMID 29201922, 2017). "The expression of TRLs in the urothelial cells plays a key role in immune response against UTIs, with TLR2, TLR4, and TLR5 considered to be most important in bacterial infections." (PMID 41596750, 2026). "The role of tlr5 in fish immunity was previously shown in relation to bacterial infection, which is because of its capacity to recognize bacterial flagellin in hosts." (PMID 38983863, 2024). "TLR5+ Lamina propria dendritic cells induced the differentiation of naive B cells into plasma cells which produced IgA through TLR5 stimulation against bacterial infection in the gut." (PMID 38473966, 2024). "When a bacterial infection takes place, host cells over-produce TLR5 to defend against such attacks." (PMID 35798038, 2023). "In the veterinary literature, several biomolecular studies on fish response to bacterial diseases demonstrated a TLR5 overexpression." (PMID 36978643, 2023). "Activation of TLR5 by flagellin triggers an immune response that helps to protect the host from bacterial infections." (PMID 37987878, 2023). "Our results showed that the expression levels of TLR4, TLR5, and MyD88 mRNA in the bladder epithelial cells were upregulated in response to the bacterial infection." (PMID 36506014, 2022). "The present study indicated that TLR5 duplicates are expressed in several tissues with similar transcription levels after a bacterial infection." (PMID 36685837, 2022). "It is well established that Toll-like receptors (TLRs), particularly surface TLRs such as TLR2, TLR4, and TLR5, play an essential role in defending against this bacterial infection." (PMID 36194127, 2022). "TLR5 recognizes flagellin of various bacteria, and increases neutrophil infiltration in animal models of bacterial infection." (PMID 34913612, 2022). "TLR5 plays a critical role in connecting innate and adaptive immunity in other bacterial infections." (PMID 28475641, 2017). "Anti-infective properties reported for flagellin (and likely also relevant for entolimod due to its similar mechanism of action) are consistent with its general role as a trigger of TLR5-mediated innate immune response to bacterial infection." (PMID 26367124, 2015). "It is possible that excess stimulation of TLR5 or the inflammasome during mucosal infection leads to the preservation of mucosal integrity, which is further enhanced by the better control of the bacterial infection." (PMID 23977202, 2013). "Although some studies suggest that TLR5 is critical in maintenance of intestinal immune homeostasis and host defense against bacterial infection, how TLR5 gene expression is regulated and its function in the mucosa have not been fully elucidated." (PMID 22545147, 2012). "Because TLR5 increases neutrophil infiltration in animal models of bacterial infection, histopathological evidences of acute inflammation could be used as surrogate markers for sensitivity to H. pylori eradication therapy." (PMID 34913612, 2022). "Moreover, the expression patterns and primary functions of the fish TLR5 genes after bacterial infection were identified." (PMID 36685837, 2022).
bacterial infection (continued). "Furthermore, our study supports a scenario wherein TLR5 on bipotent MΦ/OC myeloid progenitors helps replenish MΦs for protection against bacterial infection at mucosal sites." (PMID 33815375, 2021). "Future studies should address whether TLR5-mediated MΦ differentiation from myeloid progenitors promotes host protection against bacterial infection." (PMID 33815375, 2021). "Further research will be required to investigate the probably more complex role of TLR5 in the CNS and to establish clinical consequences of CNS injury triggered by this receptor in distinct CNS disorders, such as bacterial infection and neurodegenerative diseases." (PMID 32912327, 2020). "Also in mammals and chicken, TLR5 plays an important role in host defense against bacterial infections." (PMID 27199963, 2016). "Furthermore, bacterial infection was simulated using flagellin (agonist of TLR5)." (PMID 36830955, 2023). "In addition, significant Tlr-5 upregulation was found prior to 6 h post-bacterial infection." (PMID 31836758, 2019). "During bacterial infection, flagellin produced by bacterial pathogens is able to bind Toll-like receptor (TLR) 5 and trigger TLR5-mediated signaling." (PMID 39670709, 2025). "Among the antigen-presenting cell cluster, Toll-like receptor (TLR) expression patterns suggested a response tuned more toward bacterial infection (higher TLR4 and TLR5 expression)." (PMID 35962188, 2022). "We aimed to evaluate the expression of TLR4 and TLR5 genes in IPEC-J2 cells, as epithelial TLR expression appears to be key in the host defense against bacterial infection." (PMID 36556320, 2022). "Upon bacterial infection, splenic neutrophils and Ly6G+ CD11b+ myeloid cells from burn mice had significantly reduced TLR2, TLR4 and TLR5 expression compared to uninfected burn and infected sham mice." (PMID 24454904, 2014). "In fish, two tlr5 genes (tlr5M and tlr5S) and nod1 mRNAs were up-regulated notably after bacterial infection." (PMID 33732247, 2021). "Our study supports a scenario in which bacterial infection at mucosal sites leads to the attraction of myeloid progenitors from the blood into the infected site, where a PAMP (Flagellin) stimulates these progenitors via their own PRR (TLR5) to spin off MΦ progeny." (PMID 33815375, 2021). "TLR2, TLR4, and TLR5 play important roles in bacterial infection: TLR4 recognizes LPS, a major cell wall component of Gram-negative bacteria, whereas TLR2 and TLR5 recognize peptidoglycan (PGN), another bacterial wall component, and flagellin (FLG), respectively." (PMID 22367599, 2012).
metabolic disease (13 papers, 2015 to 2025). A congenital disorder (due to inherited enzyme abnormality) or acquired (due to failure of a metabolically important organ) disorder resulting from an abnormal metabolic process. "Fecal transfer from the Toll-Like Receptor 5 (TLR5) deficient mice to wild-type germ-free mice mimics multiple symptoms of metabolic disease in the recipient mice." (PMID 29142285, 2017). "This provides insight into therapeutic strategies aimed at modulating TLR5 signalling to prevent or manage metabolic disorders." (PMID 40444793, 2025). "This highlights the dual role of TLR5 in the mediation of gut-adipose tissue crosstalk and underscores its potential as a target for addressing inflammation-driven metabolic disorders." (PMID 40444793, 2025). "For example, an injection of flagellin can improve blood glucose control in mice by engaging TLR5 and adaptive immune responses that can protect against aspects of inflammatory and metabolic diseases." (PMID 34839023, 2022). "State-of-the-art mouse models recently highlight the involvement of Toll-like receptor 5 (TLR5)–driven microbiota composition in the development of metabolic disorders." (PMID 32715918, 2020). "The ability of TLR5 to maintain the gut microbiota composition suggests that its dysfunction may exacerbate microbial dysbiosis, a common characteristic of metabolic disorders." (PMID 40444793, 2025). "Such an hypothesis is analogous to models of intestinal immune-deficiency caused by genetic deletion (e.g. TLR5-deficiency, ASC-deficiency) which result in penetration of bacterial products and the development of metabolic disease." (PMID 25837594, 2015). "Furthermore, understanding the mechanisms by which TLR5 activation extends healthspan could provide valuable insights into therapeutic strategies for enhancing longevity and managing age-related metabolic disorders." (PMID 39957532, 2025). "We speculate that an imbalance of TLR5 signaling drives metabolic diseases." (PMID 35984746, 2022).
inflammation (8 papers, 2012 to 2023). Aberrant reaction of the microcirculation characterized by movement of fluid and leukocytes from the blood into extravascular tissues. "That the complete absence of a microbiota (i.e. germfree conditions) eliminates all evidence of inflammation in TLR5-deficient mice demonstrates that this model of gut inflammation is microbiota-dependent." (PMID 29617463, 2018). "For example, flagellin levels have been reported to be elevated in several murine models of intestinal inflammation, and flagellin can activate pro-inflammatory gene expression via TLR5 and the NLRC4 inflammasome." (PMID 34732258, 2021). "A recent study found that transient colonization with AIEC is sufficient to trigger chronic intestinal inflammation in genetically susceptible hosts–mice lacking Toll-like receptor 5 (TLR5), the sensor for bacterial flagellin." (PMID 27092122, 2016). "In addition, this could explain why those dogs carrying the TLR5 RP haplotype produce significantly less CXCL8 and are therefore less susceptible to the development of chronic intestinal inflammation such as in IBD." (PMID 22279566, 2012). "Indeed, the observation that flagellin does not promote wound healing, unlike alternative microbial products tested, may be a functional consequence of increased TLR5-driven TNF-α, with increased SOCS3, observed in chronic intestinal inflammation, exacerbating pathological TNF-α secretion." (PMID 25377316, 2015).